FGF19 (fibroblast growth factor 19)
Diseases named in the same sentence as FGF19 in open-access papers (continued):
Sharing a sentence is not in itself a finding about the gene and the disease.
tumor (continued). "In particular, we demonstrate that blockade of the IL-6/STAT3 axis eliminates FGF19-induced tumour formation without compromising the metabolic functions of FGF19 in regulating bile acid, glucose and energy homoeostasis." (PMID 28508871, 2017). "Similar elevated levels of FGF19 were observed in tumour samples and adjacent non-tumour tissues, resembling results observed in mouse models." (PMID 28508871, 2017). "It has been shown that FGFR4 has a non-substitutable role in modulating FGF19 activity to liver such as tumor growth and development." (PMID 26498355, 2016). "Open trials with FGF19 and FGFR4 inhibitors in various tumours." (PMID 28943626, 2015). "In this study, we hypothesized that the FGF19/FGFR4 system is activated in patients with HCC and is correlated with the aggressiveness of the tumor." (PMID 22309595, 2012). "In addition, the member genes FGF19, GAS2, BMP7, TNFSF11, and FGFR3 are all known to play important roles in tumor genesis and progression." (PMID 22863767, 2012). "Furthermore, it has been previously demonstrated that ectopic expression of FGF19 (i.e. FGFR4-specific ligand) in mice promotes hepatocyte proliferation, hepatocellular dysplasia, and neoplasia." (PMID 22615798, 2012). "Furthermore, ectopic expression of FGF19 (i.e. FGFR4-specific ligand) in mice promotes hepatocyte proliferation, hepatocellular dysplasia, and neoplasia and FGF19-induced hepatocyte proliferation has been reported to be uniquely mediated by FGFR4." (PMID 22615798, 2012). "More importantly, the pericentral BrdU staining seen in the wild type FGF19 group was absent in the FGF19-7 group and no tumor formation was observed in the latter indicating that the FGF19 variant had lost the ability to induce liver tumor formation." (PMID 22457778, 2012). "FGF19 staining was observed in the cytoplasm of tumor cells and noncancerous hepatocytes, and tended to be greater in the tumor cells." (PMID 22309595, 2012). "The activation of the FGF19/FGFR4 signaling pathway increases the infiltration of TAMs and myeloid-derived suppressor cells (MDSCs) while decreasing the accumulation of CD8+ T cells, leading to the formation of an immunosuppressive microenvironment that favors tumor progression." (PMID 41328353, 2026). "However, it is becoming increasingly clear that the oncogenic impact of FGF19 is not a one-size-fits-all phenomenon but rather a highly context-dependent process that varies significantly across different tumor types." (PMID 41328353, 2026). "Moreover, mice with forced FGF19 overexpression develop hepatic tumors while targeting of FGFR4, the main FGF19 receptor in the liver, reduces tumor growth." (PMID 38228803, 2024). "In addition, analysis of tumor transcriptomes suggests that induction of EMT, SMAD protein signal transduction, reorganization of extracellular matrix and vasculogenesis are enriched in FGF19/Aldafermin + MYC driven tumors." (PMID 38228803, 2024). "Similarly, by spatial transcriptomics, FGF19+ spots were overrepresented in the embryonal clusters in both HB4 and HB17, accounting for ~7-8% of the embryonal cluster while representing only ~2% of the tumor as a whole." (PMID 39567523, 2024). "In addition, co-targeting FGFR4 and CDK4/6 could significantly inhibit FGF19-driven LUSC proliferation and tumor growth in vitro and in mouse models." (PMID 35463335, 2022). "Thus, IL-1β restrained FGF19/FGFR4-induced MAPK phosphorylation and tumor generation." (PMID 33981224, 2021). "In addition, FGF-19 is highly expressed in mesenchymal stem cell-derived exosomes, which can induce the EMT through activation of the NPC cell FGF-19/FGFR-4 signaling pathway and promote tumor cell progression." (PMID 30954079, 2019). "We hypothesized that KLb plays a role as a tumor promoter, together with FGF21 or FGF19." (PMID 29731962, 2018).
tumor (continued). "The observation that FGF19 induced liver tumors was made with a transgenic model, thus potential developmental contributions of the transgene to tumor formation could not be ruled out." (PMID 22457778, 2012). "We demonstrate here that FGFR4 is required for FGF19-mediated liver tumorigenesis in vivo and show that treatment with an FGFR4 neutralizing antibody inhibited FGFR4-mediated signaling, proliferation, and colony formation in cell-based assays and tumor growth in preclinical models of HCC in vivo." (PMID 22615798, 2012). "When lean and tumor-prone FVB mice were challenged with a supra-therapeutic dose by combination of continuous infusion and daily injection, FGF19v induced only a two-fold increase in hepatic BrdU incorporation compared with vehicle-treated mice, whereas FGF19 induced on average >9 fold increase." (PMID 21437243, 2011). "Moreover, high intratumor heterogeneity inherent to HCC may explain why in various instances, the suppression of the FGF19/FGFR4 pathway did not result in an objective tumor response." (PMID 35655320, 2022). "A subcutaneous CRC cell line-derived xenograft model revealed that FGF19 is detectable in serum of mice injected with FGF19-positive, but not negative, CRC cells at levels corresponding to tumor volume." (PMID 41631414, 2026). "FGFR1-3 inhibition with AZD4547 showed significant anti-tumor effects in EOC models but not in cells highly expressing c-Met and FGF19/FGFR4, which can be treated with either c-Met and/or FGF19/FGFR4 inhibition in combination with AZD4547." (PMID 38273381, 2024). "Alterations in IDH1, FGF19, RB1, and BAP1 appeared in patients with tumor size reduction, but not in those with non-responding tumors." (PMID 35311147, 2022). "Analyzing data from the primary HCC tumor cohort, we also observed a lack of correlation between FGFR4 protein or mRNA expression and FGF19 gene expression levels." (PMID 35433463, 2022). "To determine whether HMGA1 and FGF19 are relevant in human PDAC, we queried published data sets (GSE15471; n = 36 nonmalignant tissue, n = 36 tumor samples)." (PMID 36919699, 2023). "Therefore, in order to investigate the expression of FGF19, and the correlation between FGF19 and FGFR4, which is the main receptor for FGF19, 92 HCC tumor and adjacent non-tumor tissue samples were subjected to immunohistochemical analyses." (PMID 33674622, 2021).
cancer (83 papers, 2012 to 2026). A tumor composed of atypical neoplastic, often pleomorphic cells that invade other tissues. "In clinical settings, elevated serum levels of FGF19 are associated with higher Gleason grades of PCa, a measure of cancer aggressiveness." (PMID 41328353, 2026). "Recently, it has been reported that fibroblast growth factor 19 (FGF19) stimulates inflammatory cancer-associated fibroblasts (iCAFs), which promote neutrophil infiltration and facilitate NET formation in the liver metastatic niche." (PMID 39795864, 2024). "FGF19 mediates the polarization of hepatic stellate cells to inflammatory cancer‐associated fibroblasts (iCAFs) by activating the autocrine effect of IL‐1α via the FGFR4‐JAK2‐STAT3 pathway." (PMID 37345586, 2023). "Overexpression of FGFR4 and its ligand FGF19, as well as somatic mutations, have been identified in multiple cancers." (PMID 37789421, 2023). "It has been previously reported that FGF19 is amplified in several cancer types and encodes a key autocrine signal known to promote tumorigenic growth." (PMID 33968723, 2021). "FGFR4 is highly activated in certain types of cancer and its activation is closely associated with its specific ligand, FGF19." (PMID 32154250, 2020). "High activation of FGFR4 is strongly associated with the amplification of its specific ligand FGF19 in many types of solid tumors and hematologic malignancies, where it acts as an oncogene driving the cancer development and progression." (PMID 30634399, 2019). "We subsequently aimed to investigate which proteins underlie FGF19-mediated regulation of metabolism and cell survival/cancer in the IPAs." (PMID 28178326, 2017). "For instance, cancer-associated fibroblasts (CAFs) can respond to FGF19 from HCC cells." (PMID 41328353, 2026). "In the state of cancer cachexia, metabolic dysfunction represents a hallmark, with FGF19 hypothesized to play a role in its pathogenesis by influencing metabolic pathways." (PMID 41328353, 2026). "There are multiple mechanisms that converge on FGFR4 regulation, and in addition to the direct induction caused by H. pylori protein acting on cancer epithelial cells, we have now revealed a regulatory network supported by both FGF19, the natural ligand of FGFR4, and by LIF/LIFR." (PMID 37945798, 2024). "With FGF19 having a new and detailed relationship with mitochondria and its functions as previously discussed, one can assume that FGF19 may also be intricately linked to cancers." (PMID 34572066, 2021). "Furthermore, activation of FGF19/FGFR4 signaling is closely associated with cancer development and progression." (PMID 33066597, 2020). "Because it is associated with poor outcomes of cancer, FGF19 may serve as a therapeutic target for treating cancer." (PMID 32963552, 2020). "Activation of FGF19/FGFR4 signaling is closely associated with cancer development and progression." (PMID 33066597, 2020). "Moreover, the authors observed that PXR caused FGF19 activation only in the cancer cells." (PMID 24944691, 2014). "The binding and phosphorylation mechanism of FGF19 with FGFR4 is similar in various types of cancer, including HCC and BC." (PMID 41328353, 2026). "Carcinogenic factors elevate FGF19 gene expression in OC tissues, stimulating excessive FGF19 synthesis and enhancing angiogenesis, which fuels cancer growth." (PMID 41328353, 2026). "Combining nanomedicine with FGF19-targeted therapy and delivering multiple drugs via nanoparticles will enable multi-targeted synergistic treatment, significantly enhancing cancer treatment outcomes." (PMID 41328353, 2026). "Collectively, they underscore the significant and multifaceted influence of FGF19 on cancer biology." (PMID 41328353, 2026). "Understanding the varied roles of FGF19 in each cancer type is crucial for researchers, as this understanding prompts the creation of tailored therapies targeting FGF19." (PMID 41328353, 2026).
cancer (continued). "FGF19 significantly interacts with crucial signaling pathways related to cancer, such as the PI3K/AKT and ERK/MAPK signaling pathways." (PMID 41328353, 2026). "Subsequently, we explore its roles in various cancers and discuss the therapeutic applications of targeting the FGF19/FGFR4 signaling pathway in cancer treatment." (PMID 41328353, 2026). "Overexpression of FGF19 suppresses sorafenib-induced ROS production and apoptosis, thereby enabling cancer cells to evade the cytotoxic effects of sorafenib." (PMID 41328353, 2026). "As the cancer progresses, FGF19 expression increases, suggesting its potential role in the invasive and metastatic processes of TC." (PMID 41328353, 2026). "The aim is to provide comprehensive insights into the potential of targeting the FGF19 pathway for cancer therapy, as understanding the role of FGF19 in these cancers is crucial for developing targeted therapies and improving outcomes of cancer patients." (PMID 41328353, 2026). "Abnormal activation of the FGF19/FGFR4 pathway is closely linked to poor prognosis and increased malignancy in cancers such as HCC and HNSCC." (PMID 41328353, 2026). "Elevated levels of inflammatory mediators are commonly observed in cancer cachexia, and it is plausible that FGF19 exacerbates the inflammatory milieu, thus advancing disease progression." (PMID 41328353, 2026). "These research results not only reveal the critical role of the FGF19/FGFR4 signaling pathway in cancer drug resistance but also provide a theoretical basis for the development of more effective targeted therapeutic strategies." (PMID 41328353, 2026). "Our study demonstrated that CRC cells exhibit the closest interaction with CAFs at the liver metastatic sites, where the cancer cells secrete FGF19 to promote HSCs‐to‐CAFs differentiation." (PMID 39716892, 2025). "It seems that the regenerative process of the liver following cancer requires much more intensive support for oxygenation, and the increase in FGF19 supports bile acid metabolism and the restoration of liver energy homeostasis." (PMID 39941067, 2025). "Studies have shown that aberrant FGF19 can be a driver of malignant behavior, contributing to the oncogenesis and progression of human cancers." (PMID 36751636, 2023). "In this Chinese PDAC cohort, KRAS mutations were mutually exclusive with P/LP alterations in BRAF, CTNNB1, ELF3, FGF19, and other cancer‐related genes." (PMID 36999792, 2023). "Some epigenetic drivers appeared in multiple cancers (for example, regulatory regions of ABCC1 and VEGFA; GATA6 and FOX-family motifs), whereas others were cancer specific (for example, regulatory regions of FGF19, ASAP2 and EN1, and the PBX3 motif)." (PMID 37914932, 2023). "Melatonin inhibits the progression of cancer cells by downregulating MMP-9 and fibroblast growth factor 19 to inhibit the invasion and migration of cancer cells." (PMID 38188676, 2023). "The co-amplification of FGF3, FGF4, FGF19, and CCND1was also observed in another pan-cancer study from the United States." (PMID 35494043, 2022). "Nuclear NFAT transcriptionally activates the expression of several genes including NANOG, OCT4, SOX2, and FGF19 which are involved in cancer cell stemness." (PMID 35711942, 2022). "In this study, we showed that FGF19, which has been well studied in several cancers, was involved in promoting LUSC." (PMID 35463335, 2022). "FGF19 gene amplification is common in several types of cancers, such as lung squamous cell carcinoma, breast cancer, and esophageal cancer." (PMID 33981224, 2021). "In this study, the observation that MT-LE HN30 cells progress to highly invasive cancer cells with elevated FGF19 expression prompted us to determine the specific role of FGF19 in cell aggressiveness associated with MT treatment." (PMID 33691750, 2021). "Excessive expression of the receptor and its ligand, especially FGF19, occurs in many types of cancer." (PMID 33981224, 2021).
cancer (continued). "It is suggested that a potent approach to treating different types of cancer would involve targeting the FGF19 gene to silence it." (PMID 33981224, 2021). "Amplification of the 11q13 amplicon, present in breast cancer, results in co-amplification of FGF3, FGF4 and FGF19, but is also observed in other cancer types." (PMID 34068954, 2021). "A monoclonal FGF19-blocking antibody was created to prove the function of FGF19 in cancer development." (PMID 33981224, 2021). "The blockade of FGF19/FGFR4 signaling would have great potential in improving the efficacy of melatonin supplements in cancer treatment." (PMID 33691750, 2021). "Accumulating evidence indicates that FGFR4 plays a critical role in cancer progression and metastasis, particularly in those cancer patients who have FGF19 amplification." (PMID 32154250, 2020). "We used the University of Texas Southwestern (UTSW) data set since it was based on high-quality cancer cell-enriched samples, which revealed the presence of an amplified FGF19 gene in 11 of the 109 samples in this cohort." (PMID 33066597, 2020). "Whereas AFP and DCP are markers that are comparatively highly specific for HCC, increased serum FGF19 levels have been reported in several types of cancers." (PMID 31718608, 2019). "Our results are similar to those of a previous report describing the role of FGF19 (another hormone-like FGF similar to FGF21) in a cancer model." (PMID 31408968, 2019). "Recently, there have been several reports about the association between FGF19 and FGFR4 signaling and cancer prognosis." (PMID 29731962, 2018). "Together, 183 proteins changed upon FGF19 treatment that were involved in different aspects of metabolism (e.g. Acot2, Acox1 and Acsl3) and 267 in cell survival/cancer (Col6a3." (PMID 28178326, 2017). "Further study is needed to clarify this mechanism of action of FGF19/FGFR4 signaling on cancer stem cells within the fatty liver microenvironment as a risk factor for HCC." (PMID 27447573, 2016). "We assayed the effect of neutralizing FGF19 on the cancer cell proliferation of MDA-MB-468 and HCC1937 cells using a previously characterized neutralizing antibody specific against FGF19 (1A6)." (PMID 27192118, 2016). "There was a remarkable increase in secreted FGF19 levels by the cancer cells when FGF19 was overexpressed." (PMID 26498355, 2016). "Even less is known on the role of circulating levels of FGF21, FGF19 or FGF23 as a cancer biomarker." (PMID 27358750, 2016). "Invasion assays were used to investigate the alteration of cancer cell invasiveness in the presence of FGF19 recombinant protein for JHH7." (PMID 22309595, 2012). "Aberrant activation of the FGF19/FGFR4 signaling pathway has been identified in many cancers." (PMID 41328353, 2026). "Furthermore, S100A16 is prominently expressed in PDAC and is crucial in promoting the proliferation, migration, and invasion of these cancer cells, with its effects being dependent on FGF19." (PMID 41328353, 2026). "Given its role in promoting EMT and bone metastasis, targeting FGF19 along with its related signaling pathways may present a novel therapeutic strategy for PCa, with the potential to mitigate cancer progression, recurrence, and the onset of bone metastases." (PMID 41328353, 2026). "The ability of the gut microbiota to modulate bile acid metabolism, thereby affecting FXR and subsequently FGF19, could have significant implications for the development and progression of FGF19-related cancers." (PMID 41328353, 2026). "Elucidating these distinct pathways can provide a more granular and comprehensive understanding of FGF19's role in cancer, ultimately revealing potential therapeutic vulnerabilities that can be exploited to target this versatile oncogenic factor more effectively." (PMID 41328353, 2026). "FGF19 signaling, closely linked to FXR activation, may protect against cancer by modulating bile acid metabolism and reducing inflammation." (PMID 41328353, 2026).